RAD51B (RAD51 paralog B)
Diseases named in the same sentence as RAD51B in open-access papers (continued):
Sharing a sentence is not in itself a finding about the gene and the disease.
ovarian carcinoma (15 papers, 2013 to 2025). A malignant neoplasm originating from the surface ovarian epithelium. "Given the observed association of RAD51B germline truncating variants with breast and ovarian cancer, we then sought to determine the phenotype and repertoire of somatic genetic alterations in cancers arising in RAD51B carriers." (PMID 34635660, 2021). "Our findings suggest that RAD51B should be considered as an addition to clinical germline testing panels for breast and ovarian cancer susceptibility." (PMID 34635660, 2021). "Further studies are warranted to confirm the role of RAD51B in conferring breast and ovarian cancer susceptibility in additional populations and to define the inclusion of RAD51B in panels for genetic risk prediction multigene assays." (PMID 34635660, 2021). "In our cohort of 3422 index breast and ovarian cancer cases, we found RAD51B loss-of-function germline variants (9/3422 cases) to be almost as common as those affecting RAD51C and RAD51D (combined 16/3422 cases)." (PMID 34635660, 2021). "To date, only three studies have reported truncating germline mutations in RAD51B: two deleterious mutations were detected among ovarian cancer cases, one splicing mutation in a breast and ovarian cancer family, and one nonsense mutation in a melanoma family." (PMID 27149063, 2016). "Frequency of RAD51B variants was significantly higher in cases (p = 0.012), which suggests RAD51B variants are associated with breast/ovarian cancer risks." (PMID 24139550, 2013). "Overall, for the RAD51B gene, one truncating mutation and one likely deleterious variant were detected in 2 out of 142 patients selected for enrichment in breast/ovarian cancer cases." (PMID 24139550, 2013). "This study identified the first RAD51B mutation in a breast and ovarian cancer family and is the first report of XRCC3 mutation analysis in breast and ovarian cancer." (PMID 24139550, 2013). "Here, we investigated whether germline loss-of-function variants affecting another RAD51 paralog gene, RAD51B, are also associated with breast and ovarian cancer." (PMID 34635660, 2021). "A number of reports have shown that RAD51B variants are poor prognostic factors in ovarian cancer." (PMID 33763357, 2021). "Notably, 9/10 of the female carriers of a RAD51B loss-of-function germline variant had a diagnosis of breast or ovarian cancer (5/2265 and 4/1157), for an odds ratio for breast and ovarian cancer susceptibility of 2.69 (95% CI: 1.4–5.3, p = 0.004)." (PMID 34635660, 2021). "Taken together, the data presented here support the notion that RAD51B loss-of-function germline variants result in increased breast and ovarian cancer predisposition and that biallelic loss of RAD51B in tumor cells leads to an HRD phenotype and potential sensitivity to HRD-targeting therapies." (PMID 34635660, 2021). "Our findings provide evidence that rare loss-of-function germline variants in RAD51B (found in 9/3422 [0.26%] consecutive breast or ovarian cancer cases who consented for germline analysis) are indeed associated with an increased risk of breast and ovarian cancer among women." (PMID 34635660, 2021). "Mutations in RAD51B, RAD51C, RAD51D and XRCC2 are known to cause hereditary breast/ovarian cancer and Fanconi anemia." (PMID 37344587, 2023). "The catalytic glutamate residue of RAD51 (RAD51E163) that is required for cleavage of the covalent β-γ phosphate bond of ATP is conserved in RAD51B (E144) and RAD51C (E161), and RAD51CE161 mutations have been linked to breast/ovarian cancers." (PMID 37344587, 2023). "Mutations in the human RAD51 paralogs (RAD51B, RAD51C, RAD51D, XRCC2, XRCC3, and SWSAP1) are found in a subset of breast and ovarian cancers." (PMID 30551670, 2018). "The present study analysed the five RAD51 paralogs (RAD51B, RAD51C, RAD51D, XRCC2, XRCC3) to estimate their contribution to breast and ovarian cancer predisposition." (PMID 24139550, 2013).
ovarian carcinoma (continued). "In this study, we analysed the five RAD51 paralogs (RAD51B, RAD51C, RAD51D, XRCC2, XRCC3) in 142 unrelated patients with breast and/or ovarian cancer to estimate their contribution to breast and ovarian cancer predisposition." (PMID 24139550, 2013). "This study identified the first RAD51B mutation in a breast and ovarian cancer family and confirmed that RAD51 paralog mutations confer breast and ovarian cancer predisposition and are rare events." (PMID 24139550, 2013). "RAD51B inactivation promotes tumorigenesis in breast and ovarian cancer." (PMID 41318657, 2025). "Though segregation data were not available, 8/13 of the RAD51B loss-of-function germline variant carriers had a first or second degree relative with breast or ovarian cancer." (PMID 34635660, 2021). "An additional 3 breast and ovarian cancer cases were not analyzed in this cohort because in additional to RAD51B germline mutations, they carried another high or moderate penetrance mutation in a cancer susceptibility gene (1 each BRCA2, RAD51D, ATM)." (PMID 34635660, 2021). "In contrast to these known cancer predisposition genes, the role of RAD51B in conferring susceptibility to hereditary breast and ovarian cancer has not yet been established." (PMID 34635660, 2021). "In conclusion, no pathogenic RAD51B mutations were identified among 172 Finnish breast or ovarian cancer patients." (PMID 27149063, 2016). "Identification of families with mutations in the RAD51B, RAD51C or XRCC3 genes and genetic testing of family members could be used to estimate the associated breast and ovarian cancer risks." (PMID 24139550, 2013). "Other mutations were uniquely enriched in HRD+ predicted cases of breast and ovarian cancers (BARD1, BRIP1, MRE11, RAD51D) and cancer cohorts outside breast and ovarian cancer (RAD51B), suggesting additional unique drivers of HRD that may be cancer-cohort specific." (PMID 35643464, 2022). "This raises the possibility that RAD51B pathogenic variants may contribute more to breast and ovarian cancer susceptibility in non-Caucasian populations." (PMID 34635660, 2021).
Fanconi anemia (9 papers, 2014 to 2023). Fanconi anemia (FA) is a hereditary DNA repair disorder characterized by progressive pancytopenia with bone marrow failure, variable congenital malformations and predisposition to develop hematological or solid tumors. "Deficiency in several of the classical human RAD51 paralogs [RAD51B, RAD51C, RAD51D, XRCC2 and XRCC3] is associated with cancer predisposition and Fanconi anemia." (PMID 31584931, 2019). "HRR alterations involve Fanconi anemia genes (PALB2, FANCA, FANCL, FANCI, FANCC), core RAD genes (RAD50, RAD51, RAD51B, RAD51C) as well as DNA damage response genes (ATM, ATR, CHEK1, CHEK2)." (PMID 36531003, 2022). "These genes include the Fanconi anemia pathway genes: FANCA, PALB2, BRIP1, RAD51C and XRCC2 and non-Fanconi anemia genes: ATM, CHEK2, NBN, RAD50, RAD51B, and RAD51D." (PMID 28202063, 2017).
prostate carcinoma (7 papers, 2015 to 2024). A carcinoma that arises from epithelial cells of the prostate gland. "Patients with prostate cancer with certain RAD51B or CDK12 SNVs, including RAD51B R47*, are FDA-approved for treatment with olaparib (a PARP inhibitor)." (PMID 38975340, 2024). "The association between the presence of polymorphisms rs1801320 and rs1801321 of RAD51, rs10483813 and rs3784099 of RAD51B, rs3218536 of XRCC2, and rs861539 of XRCC3 and the risk of prostate cancer was examined." (PMID 26339569, 2015). "Our data with RAD51B are consistent with published literature and our results with ATM are in agreement with the differential responses observed in patients with prostate cancer harboring tumors with mutations in ATM treated with olaparib when compared with those carrying BRCA2 mutations." (PMID 36969741, 2022). "The aim of the present study was to evaluate the relationship between prostate cancer risk and the presence of single nucleotide polymorphisms (SNPs) in the genes involved in HRR, that is, RAD51 (rs1801320 and rs1801321), RAD51B (rs10483813 and rs3784099), XRCC2 (rs3218536), and XRCC3 (rs861539)." (PMID 26339569, 2015). "However, considering that the occurrence of cancer is the result of complex interactions between genetic changes and environmental factors, polymorphic variants of the RAD51B, XRCC2, and XRCC3 genes other than those studied may yet have an impact on the development of prostate cancer." (PMID 26339569, 2015).
cervical carcinoma (6 papers, 2016 to 2022). A carcinoma arising from either the exocervical squamous epithelium or the endocervical glandular epithelium. "In this relatively large case–control study, we investigated the association between miRNA‐binding site variants of RAD51B and cervical cancer risk among Chinese women." (PMID 27334422, 2016). "Furthermore, genetic variants in miR-binding sites of RAD51B have been shown to be associated with cervical cancer risk." (PMID 30713603, 2019). "In this study, we aimed to investigate whether potentially functional variants within miRNA‐binding sites of RAD51B are associated with risk of cervical cancer." (PMID 27334422, 2016). "In summary, our study suggested that miRNA‐binding site genetic variants of RAD51B may modify the susceptibility to cervical cancer, which is important to identify individuals with differential risk for this malignancy and to improve the effectiveness of preventive intervention." (PMID 27334422, 2016). "Further studies with different ethnic background and biological function analyses are warranted to uncover the mechanism of RAD51B in cervical cancer development." (PMID 27334422, 2016). "It has been noted that RAD51B is disrupted by HPV integration in multiple cervical cancer samples, which is consistent with our results." (PMID 27363024, 2016). "Up-regulation of ENST00000503812 may inhibit RAD51B and IL-28A expression and result in deficiency of DNA repair pathway and immune responses in HPV-16 positive cervical cancer cell." (PMID 27363024, 2016). "We showed that four miRNAs (miR-502, miR-145, miR-142, and miR-33b) are independent and common prognostic biomarkers for patients with cervical cancer, and seven proteins (CXCL12, IGF1, PTPRC CDH5, RAD51B, REV3L, and WDHD1) are key genes significantly related to lymph node metastasis." (PMID 32457603, 2020). "Also, the expression levels and/or roles of miR-142, miR-33b, RAD51B, REV3L, and CDH5 in cervical cancer lymph node metastasis need further clarification." (PMID 32457603, 2020). "In cervical carcinoma, VTCN1 exhibited a negative correlation with OGG1 and RAD51B methylation that was statistically significant after Bonferroni correction (p=0.009, p=0.015, respectively)." (PMID 27683114, 2016).
lung carcinoma (6 papers, 2017 to 2025). "Promoter methylation of RAD51B seems to associate with PD-L1 expression in lung cancer patients, with high levels of RAD51B methylation associating with lower risk of disease progression." (PMID 33761971, 2021). "For SNP pair rs74826777:rs1474960, from RGL1:RAD51B gene pair, individuals with genotype 1/0 had a lung cancer risk effect with OR 1.31 and p value 0.01 whereas individuals with genotype 1/1 had a reduced effect with OR 0.51 and p value 6.46x10-7." (PMID 30956756, 2019). "In contrast, RAD51B SVs were associated with a significant increase in FGA in only breast (BRCA), head and neck cancer (HNSC) and lung cancer (LUAD) using data from the TCGA." (PMID 40369102, 2025). "We successfully identified epistasis in RGL1:RAD51B in ALL and NSCLC lung cancer, SYNE1:RNF43 in ADE and FHIT:TSPAN8 in SQC risk development." (PMID 30956756, 2019). "Interestingly, all the three significant epistasis—-RGL1:RAD51B in ALL and NSCLC lung cancer, SYNE1:RNF43 in ADE and FHIT:TSPAN8 in SQC risk development—-were displayed as interaction between networks." (PMID 30956756, 2019). "The function of RAD51B in cancer cell lines has not been well studied and most previous work has rarely mentioned the association between RAD51B and lung cancer." (PMID 29207658, 2017). "However, no prior research has proposed a link between the expression of RAD51B gene and lung cancer." (PMID 29207658, 2017). "For the genetic interaction between RGL1 and RAD51B gene, we identified 7 and 3 SNP pairs with joint p value < 1.95x10-10 from the ALL lung cancer and NSCLC cohort, respectively." (PMID 30956756, 2019). "In NSCLC lung cancer cohort, IPA created two top gene networks with RAD51B in one network and RGL1 in the other." (PMID 30956756, 2019). "Interestingly, the data have shown several fold upregulation of DNA repair genes like RAD51b, RAD 18 and SOX2 cancer stem cell markers, MUC5AC and TGFBR2 in radiation resistant and caveolin-1, overexpressed A549 lung cancer cells." (PMID 34762666, 2021). "Take the rs74826777:rs17835244 pair from RGL1:RAD51B gene pair as an example, these two SNPs had p value of 0.16 and 0.02 in single-locus association analysis in ALL lung cancer cohort, respectively, indicating no significant main effect in lung cancer development." (PMID 30956756, 2019).
squamous cell carcinoma (6 papers, 2016 to 2021). A carcinoma arising from squamous epithelial cells. "In the stratified analysis, overexpression of RAD51B was prominently associated with the decreasing death risk of death for patients with squamous cell carcinoma (HR=0.68, 95%CI: 0.51∼0.90)." (PMID 29207658, 2017). "Furthermore, epigenetic alterations in RAD51B, specifically DNA promoter methylation, were associated with PD-L1 expression in squamous cell carcinomas." (PMID 32252414, 2020). "We therefore conclude that hypermethylation of homologous recombination DNA repair genes including RAD51B and XRCC3 is associated with an inflamed phenotype in squamous cell cancers of the head and neck, lung and cervix." (PMID 27683114, 2016). "We are yet to unravel the mechanisms underlying this phenomenon, but the results suggest that RAD51B might be a novel marker, particularly useful for the NSCLC patients with squamous cell carcinoma." (PMID 29207658, 2017). "After stratification analysis, RAD51B overexpression was also found to be associated with the increasing OS in the patients with squamous cell carcinoma (P=0.0076), but this association was not shown in the adenocarcinoma patients (P=0.6244)." (PMID 29207658, 2017). "Further, the multivariate Cox regression analysis showed that the morbidity of patients with high expression of RAD51B was decreased by 26% compared to those with low expression (HR=0.74, 95%CI: 0.59-0.93), especially for the patients with squamous cell carcinoma (HR=0.68, 95%CI: 0.51-0.90)." (PMID 29207658, 2017). "Interestingly, RAD51B and XRCC3 promoter methylation has been reported in association with the inflamed phenotype of squamous cell carcinomas of the head and neck, lung, and cervix, warranting further investigation as predictive biomarkers of response to immunotherapy." (PMID 32295201, 2020). "Furthermore, after adjustment for some potential confounding factors, the multivariate Cox regression analysis showed that the death risk of patients with high expressions of RAD51B decreased by 26% compared to those with low expression, especially for NSCLC patients with squamous cell carcinoma." (PMID 29207658, 2017). "It was found that in 2,616 coding genes, 2 or more integration sites presented among samples, like RAD51B, MACROD2, FHIT, CSMD1, LRP1B, and DLG2, which had already been previously reported as frequent sites of integration in squamous carcinoma samples." (PMID 33810183, 2021). "Nevertheless, our results provide statistical evidence for RAD51B as an independent factor affecting the prognosis of NSCLC, especially for the patients with squamous cell carcinoma." (PMID 29207658, 2017). "Two homologous recombination genes, X-Ray Repair Complementing Defective Repair in Chinese Hamster Cells 3 (XRCC3) and RAD51 Paralog B (RAD51B) exhibited the highest correlation with CD274 and CTLA4 across all three squamous cell cancer types." (PMID 27683114, 2016).
Uterine leiomyoma (6 papers, 2013 to 2024). The presence of a leiomyoma of the uterus. "Nevertheless, more data is needed to confirm the possibility of RAD51B altered uterine leiomyoma as a distinct molecular subtype." (PMID 37466765, 2024). "In our study, we described two cases of uterine leiomyoma with RAD51B::NUDT3 fusion, which occur in one case of usual-type and one case of cellular leiomyoma." (PMID 37466765, 2024). "In our study, we described two cases of uterine leiomyoma with RAD51B::NUDT3 fusion, which occur in one case of usual and one case of highly cellular leiomyoma." (PMID 37466765, 2024). "In uterine leiomyoma, the phenomenon of frequent inactivation of RAD51B by translocation between chromosomes 12 and 14 was noticed, supporting a positive role of RAD51B in tumorigenesis." (PMID 29207658, 2017). "Inactivation of RAD51B by translocation between chromosomes 12 and 14 is a frequent finding in uterine leiomyoma, supporting a role for the inactivation of RAD51B in tumorigenesis." (PMID 26339569, 2015). "More generally concerning RAD51B involvement in cancer, previous studies have identified chromosomal rearrangements disrupting RAD51B in benign tumours, particularly uterine leiomyomas." (PMID 24139550, 2013). "RAD51B::NUDT3 fusion should be added to the spectrum of fusions which may occur in uterine leiomyoma, which can be of value especially in cellular leiomyoma in the context of differential diagnosis against endometrial stromal tumors." (PMID 37466765, 2024). "In uterine leiomyomas, HMGA2 fusion transcripts were reported with various sequences including COX6C (8q22.2), ALDH2 (12q24.12), CCNB1IP1 (14q11.2), RAD51B (14q24.1), and RTVL-H 3_ LTR (21q21.2)." (PMID 28591699, 2017). "While it has been suggested that alteration of HMGA2 is considered to be the initial step leading to significant upregulation of PLAG1, the role of RAD51B should not be overlooked, as it is also important in uterine leiomyoma development." (PMID 37466765, 2024). "Another study comparing uterine leiomyoma and leiomyosarcoma found that a small percentage (3 out of 56) of leiomyoma cases showed a RAD51B fusion (with HMGA2, NCOR2, and NUDT3), and one of these cases with RAD51B::NUDT3 fusion is reported here in detail." (PMID 37466765, 2024).
age-related macular degeneration (4 papers, 2015 to 2024). Age-related loss of vision in the central portion of the retina (macula), secondary to retinal degeneration. "The relationship between the RAD51B gene rs10483813 polymorphic variants and risk of triple-negative breast cancer and age-related macular degeneration has also been indicated." (PMID 26339569, 2015).
colorectal cancer (4 papers, 2017 to 2023). A primary or metastatic malignant neoplasm that affects the colon or rectum. "NEDD4, CNOT6L, and DNA repair protein RAD51 homolog 2 (RAD51B) were previously associated with IBD, tuberculosis, and colorectal cancer, respectively." (PMID 37512987, 2023). "Although a segregation analysis would be required to assess the carrier status of relatives with colorectal cancer, to our knowledge, there has been no report of the association of RAD51B variant with the familial risk of colorectal cancer." (PMID 31780696, 2019).